CCR2 (C-C motif chemokine receptor 2)
Diseases named in the same sentence as CCR2 in open-access papers (continued):
Sharing a sentence is not in itself a finding about the gene and the disease.
tumor (continued). "A natural CCR2 antagonist from Abies georgei could elevate the number of CD8+ T cells in tumors via blocking tumor-associated macrophage-mediated immunosuppression to potentiate the therapeutic effect of sorafenib for liver cancer." (PMID 31572568, 2019). "High CCL7 expression evokes the recruitment of tumor-associated macrophages (TAMs) that express CCR2 on the surface, resulting in the persistence of increased vascular permeability; therefore, tumor cells can cross the blood–brain barrier and move toward brain tissues." (PMID 29915688, 2018). "Moreover, these tumors are also highly enriched in factors that recruit or support suppressive monocytic MDSC or tumor associated macrophage populations (CCR2, CSF1R, and GM-CSF/CSF2)." (PMID 30388137, 2018). "Likewise, in a recent study utilizing a mouse model of colorectal cancer, tumor-associated macrophages derived from CCR2+ monocytes played a crucial role in development of the extracellular matrix, revealing a novel pro-tumor mechanism for macrophages." (PMID 28382036, 2017). "Similarly, therapeutic blocking of CCL2/CCR2 axis against hepatocellular carcinoma inhibited the recruitment of inflammatory monocytes and tumor-associated macrophages, resulting in the reversal of the immunosuppressive TME and inactivation of antitumoral CD8+ T cell responses." (PMID 38786066, 2024). "Indeed, tumour-associated myeloid cells from patients frequently express CCR2." (PMID 36161514, 2023). "Interestingly, no downregulation of chemokines other than CXCL12 was found by Tranilast administration, though it is well known that CCL2 (MCP-1) is a major chemoattractant for recruiting monocytes, causing increased CCR2-expressing macrophage migration into the tumor site." (PMID 34997450, 2022). "Additionally, tumor-associated macrophages (TAMs) in mouse lungs were shown to be tissue-resident IM and CCR2-dependent recruited macrophages, with the former mainly promoting tumor growth in—among others- an IL-9-dependent manner, and the latter facilitating tumor cell dissemination." (PMID 36305904, 2022). "In addition, CCR2 deficiency prevented tumour cell extravasation." (PMID 34464477, 2021). "Thus the CCR2-64I variant would be associated with increased risk of cancer in the later stage of tumour development (in this situation after progressing to HSIL) when compared to the CCR2-64V variant which is associated with less stable CCR2A stability and expression." (PMID 20537184, 2010). "Within the tumor microenvironment, gene expression profiling revealed upregulated chemokine signaling pathways (CCR2/CCL7, CXCR6/CXCL16) and key immunosuppressive markers, including PD-L1 and TGF-β1." (PMID 42227811, 2026). "Although the exact mechanism of how MDSCs are recruited to tumor sites is not fully understood, growing evidence suggests that chemokine receptors, especially the chemokine receptor 2 (CCR2), play a key role in this process." (PMID 41561738, 2025). "The overexpression of CCL2 chemokine in tumours like glioblastoma, bladder, prostate, breast, ovarian, gastric, melanoma and renal cell carcinoma facilitates the recruitment of CCR2+ LY6C+ M-MDSCs, causing a higher tumour load and reduced overall survival." (PMID 40852716, 2025). "CCR2 antagonists have been demonstrated to possess limited inhibitory effects on tumor growth in isolation." (PMID 40109347, 2025). "Here, using a preclinical orthotopic PDAC tumor model, we provide direct evidence that iIRE treatment induces a CCR2+ TAM-mediated immunosuppressive microenvironment in the residual tumor, ultimately accelerating tumor progression." (PMID 40700478, 2025). "CCL2 facilitates the recruitment of MDSCs to tumors and promotes immunosuppression in a CCR2-dependent manner, ultimately contributing to tumor growth." (PMID 41368628, 2025).
tumor (continued). "TAM can be derived from blood monocytes that migrate into the tumour following a variety of chemotactic signals (mainly produced by tumour cells), such as macrophage colony-stimulating factor (M-CSF, CSF-1), CCR2, and VEGF." (PMID 40385641, 2025). "This demonstrates translational potential to liver tumors as CCR2 has been shown to be involved in multiple stages of liver pathology including tumor progression." (PMID 40636106, 2025). "Those monocytes are recruited to the tumor by C-C motif ligand (CCL) 2 - C-C motif chemokine receptor 2 (CCR2) signaling." (PMID 40165290, 2025). "In the TME, elevated CCL2-mediated chemotaxis recruits CCR2+ circulating monocytes to the tumor site, thereby contributing to the establishment of an immunosuppressive TME." (PMID 40700478, 2025). "Both Gal-3 and CCL2 enhanced the formation of tumor spheres, and this process was inhibited by the CCR2 inhibitor." (PMID 40600063, 2025). "Mechanistically, Roscovitine decreased PD-L1 expression on tumor cells and myeloid populations, including circulating and tumor-infiltrating MDSCs, while reducing CCR2+ MDSC frequency in circulation." (PMID 41561738, 2025). "(In the process of vascularization, CCL2 binding to CCR2 on tumor cells triggers ILK and MEK1/2 pathways, inhibits miR-29c to promote the generation of VEGF-A, and further promotes the formation of neovascularization." (PMID 41445742, 2025). "Synergistically, the CCL2/CCR2 axis reinforces this immunosuppressive milieu by attracting macrophages with tumor‐promoting phenotypes." (PMID 40145607, 2025). "GBM cells and tumor-associated endothelial cells secrete CCL2, which binds to CCR2 on circulating CX3CR1+CCR2+ monocytes, facilitating their transmigration across the blood–brain barrier into the tumor microenvironment." (PMID 41002423, 2025). "Inflammatory monocytes expressing CCR2 are actively recruited to metastatic lungs, where they promote tumor cell extravasation, metastatic outgrowth, and an immunosuppressive environment." (PMID 39566333, 2025). "We observed transient depletion of circulating CCR2-expressing cells, such as monocytes and MDSCs, and increased activation of DCs and effector T cells in tumor-bearing mice after treatment with mTAK-500." (PMID 39918395, 2025). "The quantification of fluorescently labeled cell clusters in the lungs revealed a substantial increase of Ccr2-/- monocytes both in tumor bearing BL6 and Ccr2-/- mice, when compared to naïve mice." (PMID 39566333, 2025). "The recruitment and differentiation of inflammatory monocytes into tumor-associated macrophages, which can facilitate metastasis, are mediated by the CCR1 and CCR2 chemokine axes [3,7,]." (PMID 39566333, 2025). "Tumor cells release CCL2, a potent chemoattractant for CCR2-expressing myeloid cells, including tumor-associated macrophages (TAMs) and myeloid-derived suppressor cells (MDSCs)." (PMID 40867316, 2025). "Using CCR2-KO mice, we assessed tumor progression in TRPC- and TSC-derived tumors under conditions of diminished macrophage infiltration." (PMID 40661379, 2025). "Myeloid-derived suppressor cells overexpress CCR2 and are preferentially recruited to the tumor microenvironment, where they support tumor cell dissemination and inhibit T-cell function 25-27." (PMID 41049010, 2025). "CCL2 and its receptor CCR2 promote tumor cell proliferation and metastasis by attracting monocytes and macrophages in the tumor microenvironment." (PMID 40918470, 2025). "CCR2 plays a crucial role in regulating M-MDSC function in cancer by affecting tumor growth, metastasis, and immunotherapy resistance." (PMID 39891718, 2025). "For instance, engineering anti‐MSLN CAR T cells to express the chemokine receptor CCR2 enhances their migratory capacity toward the tumor site." (PMID 40904706, 2025). "During carcinogenesis, malignant cells release CCL2 to recruit CCR2-positive classical monocytes and Mo-MDSCs to promote tumor growth and progression." (PMID 40427136, 2025).
tumor (continued). "Chemokine ligand 2 (CCL2) recruits monocytes expressing chemokine receptor 2 (CCR2) from the peripheral blood to the tumor site, where they further mature into TAMs." (PMID 40191203, 2025). "In MC38 tumours, both Ly6C+ and Ly6C–F4/80high TAM subsets are affected by Ccr2-deficiency, but F4/80high TAMs are better preserved." (PMID 40523200, 2025). "In murine tumor and metastasis models CCR2 antagonism in combination with anti‐PD‐1 therapy leads to sensitization and enhanced tumor response over anti‐PD‐1 monotherapy." (PMID 39988712, 2025). "CCL2, in particular, mediates the recruitment of CCR2-expressing monocytes from the bloodstream into the tumor bed, where they subsequently mature into TAMs." (PMID 41058699, 2025). "CAR T-cells transduced with CCR2b, the dominant isoform of CCR2, showed improved tumor infiltration and tumor control in mouse models, including successfully crossing the blood-brain barrier to control brain metastases from NSCLC." (PMID 41019052, 2025). "We show that IFNγRKO tumours were dominated by inflammatory monocytic and pre-macrophage subsets compared to archetypal TAMs in WT tumours, and this mechanism relied on CCR2-dependent myeloid recruitment." (PMID 39746898, 2025). "The expression of CCR2, a chemokine receptor on the surface of M-MDSCs, regulates their migration toward tumors and promotes tumor progression." (PMID 39891718, 2025). "The CCL chemokines CCL2, CCL7, CCL8, and CCL12 are known ligands for CCR2 expressed on circulating monocytes and facilitate their recruitment into the tumor microenvironment." (PMID 40867322, 2025). "Another approach is enhancing macrophage homing to tumours by upregulating chemokine receptors like CCR2 or CXCR3, which can significantly improve CAR-M migration and retention at tumour sites, thereby boosting therapeutic efficacy." (PMID 40624498, 2025). "CCL2 has the ability to draw CCR2-positive monocytes into the tumor microenvironment, prompting their differentiation into TAMs, ultimately fostering tumor growth and metastatic processes." (PMID 41394878, 2025). "Combining CCR2 antagonism with anti-PD-1 therapy has demonstrated improved tumour responses in solid tumours resistant to ICI monotherapy." (PMID 40683913, 2025). "In the MPM mouse model, CCR2-transduced CAR-T cells show enhanced tumor infiltration and antitumor efficacy." (PMID 40148310, 2025). "As observed, there was a significant reduction in CCR2+F4/80+ colocalized areas within the tumor region, accompanied by a notable increase in CD8+ areas." (PMID 40700478, 2025). "As observed with chemotherapy, radiotherapy similarly alters the phenotype of CCL2/CCR2-recruited monocytes towards tumor-supporting Mo-MDSCs, which promotes radioresistance." (PMID 41440002, 2025). "For example, expressing target tissue-specific receptors (such as tumor-highly expressed CXCR4 or CCR2) on the cell surface through genetic engineering can enhance its interaction with the lesion microenvironment." (PMID 40650096, 2025). "M2 macrophages secrete CCL2, which binds to CCR2 on tumor cells and activates the MEK–ERK–ELK1 axis, leading to increased SNAIL expression and a more invasive phenotype of GBC." (PMID 40564091, 2025). "We next evaluated aNP18’s therapeutic potential by silencing C–C chemokine receptor type 2 (Ccr2) expression in a syngeneic tumour mouse model." (PMID 39900620, 2025). "When CCL2 binds to the C-C chemokine receptor type 2 (CCR2) on the tumor cells, it enhances mobility and directs their infiltration into brain tissue." (PMID 39858080, 2025). "The number of macrophages in BL6 mice injected with LLC1.1-Ccl2KD tumor cells was comparable to Ccr1-/- or Ccr2-/- mice injected with LLC1.1-wt, suggesting that both chemokine axes act in a subsequent manner." (PMID 39566333, 2025). "CCL2 is overexpressed in tumor cells while its receptor CCR2 is exclusively expressed in immunosuppressive cells, conferring CCL2-CCR2 as an oncogenic axis." (PMID 40148310, 2025).
tumor (continued). "The quantitative analysis of CCR2 protein levels across tumor types showed a wide range of scores with consistently higher expression in NSCLC samples, followed by PDAC samples, and lower levels in CRC samples." (PMID 39918395, 2025). "Spatially resolved analysis of CCR2 and immune cell markers in the tumor microenvironment of >1,000 primary human tumors showed that the CCR2 protein was predominantly expressed in intratumoral myeloid cells." (PMID 39918395, 2025). "To test the effect of individual Ccr1- and Ccr2-deficiences, we tested LLC1.1 tumor cells in an experimental lung metastasis model using BL6, Ccr1-/-, and Ccr2-/- mice." (PMID 39566333, 2025). "The recruitment of both BL6 and Ccr2-/-monocytes was increased in a similar ratio in tumor-injected mice, when compared to naïve mice." (PMID 39566333, 2025). "The design of CCR2+ TAM–targeted immunotherapeutic combinations was refined according to the tumor immune landscape to overcome these resistance mechanisms." (PMID 40700478, 2025). "In contrast, BMDMs primarily derive from peripheral monocytes that infiltrate the tumor core via CCR2-dependent pathways." (PMID 41002423, 2025). "In mouse models, the inhibition of CCR2 leads to a reduction in IMs and macrophages in primary tumors and in the pre-metastatic liver, thereby enhancing anti-tumor immunity, reducing tumor growth, and limiting metastasis." (PMID 40243455, 2025). "These reductions in MDSC populations and CCR2 expression are likely to diminish immune suppression within the tumor microenvironment, enhancing the therapeutic impact of anti-PD-1." (PMID 41561738, 2025). "Chemokine CCL2 is implicated in MDSC infiltration into the GBM microenvironment, enabling tumor-recruiting by CCR2+ cells." (PMID 40514725, 2025). "TRPCs formed more aggressive tumors in wild-type mice, but in CCR2-KO mice, the tumor growth advantage was negated and survival were similar between both groups." (PMID 40661379, 2025). "TAK-500, a STING agonist, activates CCR2+ myeloid cells in the tumor microenvironment and converts immune suppressive “cold tumor” into “hot tumor” characterized by CD8+ T cell proliferation and activation." (PMID 40700292, 2025). "The migration of monocytes derived from BL6, Ccr1-/- and Ccr2-/- mice was dependent on tumor cell-derived Ccl2 in the CM, since migration towards CM from Ccl2KD tumor cells was reduced." (PMID 39566333, 2025). "Tumor-associated macrophages (TAMs), comprising up to 50% of the tumor mass, are recruited via chemokine axes such as CCL2/CCR2, CX3CL1/CX3CR1, and CXCL12/CXCR4 and adopt an M2-like immunosuppressive phenotype, facilitating immune escape and angiogenesis." (PMID 41002423, 2025). "Taken together, both Ccr1- and Ccr2-dependent recruitment and stimulation of monocytes/macrophages promote metastasis, which are increased by tumor-derived Ccl2." (PMID 39566333, 2025). "In glioblastoma animal models, inhibitors targeting the CCR2/CCL2 axis have been shown to significantly reduce M2-type TAM infiltration at tumor sites, leading to improved survival outcomes." (PMID 41019045, 2025). "Previous studies have shown that the continuous treatment of tumor-bearing mice using a CCR2-blocking antibody at a dose level of 45 μg/mouse resulted in only modest antitumor activity." (PMID 39918395, 2025). "In CRC, HCAR1 signaling promotes the secretion of chemokines CCL2 and CCL7 by tumor cells, which in turn recruit CCR2+ PMN-MDSCs." (PMID 41152975, 2025). "We are also continuing to explore the best approach to understand the relative contribution of CCR2+ monocytes in the blood versus tumor myeloid cells in our observed responses." (PMID 39918395, 2025). "Exosomal CCL2 secreted by tumor cells primarily accumulates in the primary tumor, with a small amount being taken up by CCR2+ myeloid‐derived suppressor cells and CCR2+ NK cells, promoting tumor metastasis." (PMID 39712454, 2025).
tumor (continued). "To inhibit the recruitment of CCR2+ TAMs to the tumor site following iIRE, we incorporated a highly selective CCR2 inhibitor (PF-4136309), which is currently in phase 2 clinical trials for advanced PDAC, into our therapeutic strategy." (PMID 40700478, 2025). "Preclinical studies indicated that CCR2 inhibitors significantly reduced tumor metastasis and mortality in animal models." (PMID 39014433, 2024). "Further research has confirmed the efficacy of CD47 blockade agents and CCR2 inhibitors in slowing tumor growth and modulating the tumor microenvironment." (PMID 38665428, 2024). "Another study reported that CCL2 induced by hypoxic tumor cells can inhibit the maturation of NK cells in the pre‐metastatic niche and reduce their ability to eliminate incoming circulating tumor cells, thereby accelerating the homing of tumor cells to CCR2." (PMID 38468260, 2024). "Recruitment of monocytes from bone marrow to the tumor site is dependent on C-C motif ligand 2 (CCL2)-CC chemokine receptor 2 (CCR2) signal transduction." (PMID 38605951, 2024). "Paradoxically, in the tumor microenvironment, CCR2-expressing monocytes and macrophages can strongly suppress immune responses." (PMID 38650924, 2024). "The presence of CCR2+ M2 polarized macrophages has been shown to enable tumor recurrence and clinically, inhibition of CCR2+ macrophages increases CD8+ T cells." (PMID 38727236, 2024). "Gene expression profiling using NanoString technology revealed upregulation of genes encoding chemokine receptors CCR2 and CCR5, indicating enhanced migration towards tumor sites." (PMID 39660132, 2024). "High levels of CCL12 have been reported to cause the recruitment of CCR2-induced M-MDSCs to the tumor site of irradiated MC38 colon tumors and the Lewis Lung Carcinoma tumor model." (PMID 38360737, 2024). "At the cell membrane level, while Mo show high CD45 levels already in the normal brain, Mo-TAMs in PDOXs, similarly to Mg-TAMs, increased CCR2 levels in the tumor core." (PMID 38566128, 2024). "In contrast, in the early stages of HCC, immune cells such as macrophages recruited by CCR2 can prevent early tumor formation by eliminating senescent hepatocytes." (PMID 38874512, 2024). "Human umbilical cord-derived MSCs genetically modified with lentivirus to deliver ISZ-sTRAIL-induced apoptosis and reduced tumor growth in a xenograft mouse model of lung cancer that had migrated to the tumor site by the MCP-1/CCR2 axis." (PMID 39063032, 2024). "CCR2 blockers can eliminate inflammatory monocytes and macrophages at the tumor site, enhance anti-tumor immunity, and reduce tumor growth." (PMID 40458305, 2024). "Recently, a study identified a novel histone deacetylase 5 (HDAC5)-CCL2/CCR2-TGF-β/SMAD4 axis driven by epigenetic regulation to promote tumor growth in a PDAC model." (PMID 38167055, 2024). "Monocytes are recruited to tumor sites via the CCL2/CCR2 axis, inhibiting CD8+ T cell infiltration and recruiting Tregs." (PMID 39253716, 2024). "Macrophages are able to achieve targeted enrichment at tumor sites through a range of strategies, which correlate, at least in part, with the expression of CD11b and CCR2 proteins." (PMID 38195682, 2024). "Our study also provided evidence that the IL6/IL6R and CCL2/CCR2 signaling pathways within the TME exert a greater influence on the ability of HPV − tumor cells to evade immune attack by NK cells compared to HPV + tumors." (PMID 38468260, 2024). "CCL-2 receptor (CCR2) expressing monocytes are recruited along a CCL2 gradient to the tumor periphery where they mature further in the TME and develop pro-tumoral functions." (PMID 39882242, 2024). "CCR2 antagonism therapy, which prohibits recruitment of circulating monocytes into the tumour, improved tumour control based on RECIST criteria when combined with standard of care FOLFIRINOX." (PMID 38426634, 2024).